RIPK1 (receptor interacting serine/threonine kinase 1)
Diseases named in the same sentence as RIPK1 in open-access papers (continued):
Sharing a sentence is not in itself a finding about the gene and the disease.
glioma (continued). "Similar results were observed in the Chinese Glioma Genome Atlas (CGGA) dataset, where mRNA levels of RIPK1, RIPK3, and MLKL were elevated across glioma grades." (PMID 41429922, 2025). "Together, these findings demonstrate that the necroptotic genes RIPK1, RIPK3, and MLKL are robust predictors of adverse clinical outcomes across glioma subtypes." (PMID 41429922, 2025). "To investigate the role of RIPK1 and MLKL in glioma invasiveness, we performed Transwell migration and Matrigel invasion assays in U251 cells." (PMID 41429922, 2025). "To investigate the role of RIPK1 and MLKL in glioma progression, we first examined their expression in relation to proliferative activity." (PMID 41429922, 2025). "Collectively, these results demonstrate that both RIPK1 and MLKL critically support glioma cell proliferation and tumorigenesis, with RIPK1 exerting a more potent role." (PMID 41429922, 2025). "ZZW-115, an antitumor agent that triggers both apoptosis and necroptosis, and citronellol, a natural compound that promotes RIPK1/RIPK3-dependent necroptosis, were tested in U251 and U87 glioma lines." (PMID 41429922, 2025). "In this study, we demonstrate that the necroptotic machinery genes RIPK1, RIPK3, and MLKL are highly expressed in gliomas and positively correlate with disease progression and patient prognosis." (PMID 41429922, 2025). "In summary, this study identifies RIPK1 and MLKL as critical drivers of glioma progression and prognostic biomarkers." (PMID 41429922, 2025). "To assess the prognostic significance of the necroptotic genes RIPK1, RIPK3, and MLKL in gliomas, we performed survival analyses across multiple datasets." (PMID 41429922, 2025). "Here, we integrate analyses of RIPK1, RIPK3, and MLKL across clinical glioma samples and experimental models to define the contribution of the necroptotic pathway to glioma pathobiology." (PMID 41429922, 2025). "As expected, increased expression in gliomas has also been observed for TNF-α, TNFR1, RIPK1, and RIPK3." (PMID 39062119, 2024). "As shown by the bean plot, 7 genes (RIPK1, RIPK3, FAS, FADD, FASLG, TLR3, and TNF) were upregulated in the glioma tissues with p <0.001." (PMID 35719998, 2022). "Emodin, an anthraquinone derivative, has been reported to increase TNF-α, RIPK1, and RIPK3 levels in in vitro and in vivo glioma cancer models, which significantly inhibited glioma progression through necroptosis induction." (PMID 36361505, 2022). "In a rat glioma model, apoptosis was induced by activation of CASP8 and inhibition of RIPK1/RIPK3 complex." (PMID 29912993, 2018). "Since Ki67 is a well-validated marker of cellular proliferation, this finding suggests that RIPK1 and MLKL may contribute to the aggressive behavior of glioma." (PMID 41429922, 2025). "Collectively, these findings identify RIPK1 as a critical driver of glioma malignancy and underscore the therapeutic potential of activating necroptosis to augment TMZ efficacy, providing a framework for novel prognostic and treatment strategies in glioma." (PMID 41429922, 2025). "To validate these findings, we performed Western blot analyses across a clinical cohort of 81 glioma samples (16 grade II, 19 grade III, and 46 grade IV), which revealed significant upregulation of RIPK1 and MLKL and downregulation of RIPK3 in grade IV tumors relative to lower-grade gliomas." (PMID 41429922, 2025). "In the glioma tumor cells, iPA led to the activation of RIPK1, RIPK3, and MLDL, but there was no activation of caspases." (PMID 39062119, 2024). "Consistently, two vital effector molecules, RIPK1 and RIPK3 were also highly expressed in glioma, suggesting that initiation of necroptosis may be critically regulated by these highly expressed upstream NRGs in glioma." (PMID 36466844, 2022).
glioma (continued). "The high expression of TLR3 in lower grade glioma (LGG) and LUSC; FASLG in LGG, UVM, KIRC, and THYM; RIPK3 in LGG, KIRC, and LUSC; RIPK1 in LGG and THCA; FAS in LGG, UVM, and THYM; MLKL in LGG, UVM, and LUAD; FADD in LGG and HNSC; and TNF in UVM and CESC was associated with poor survival." (PMID 35748782, 2022).
lung carcinoma (19 papers, 2013 to 2025). "The present study found that the RIPK1 rs17548629 C>T mutation in young and middle-aged Han can significantly increase the risk of lung cancer and lung adenocarcinoma." (PMID 32368189, 2020). "The present general population and cytology study preliminarily verified an association between SNP variants on RIPK1 rs17548629 and lung cancer." (PMID 32368189, 2020). "The present study found that, among all pathological types of lung cancer, only adenocarcinoma was associated with the polymorphism of RIPK1 rs17548629 under the recessive genetic model." (PMID 32368189, 2020). "Under the recessive genetic model, the risk of lung cancer in carriers of the RIPK1 rs17548629 TT genotype was 1.803-fold (95% CI 1.104 to 2.944) that of the CC + CT genotype carriers." (PMID 32368189, 2020). "There have been few reports regarding associations between RIPK1 or its polymorphisms and lung cancer." (PMID 32368189, 2020). "Single-nucleotide polymorphism rs17548629 in RIPK1 may be associated with the formation of lung cancer." (PMID 35907206, 2022). "RIPK1 rs17548629 mutation (T) may increase the risk of lung cancer in young and middle-aged Han people under co-dominant and recessive genetic models, and increase the risk of lung adenocarcinoma in recessive genetic models." (PMID 32368189, 2020). "However, the present results warrant experiments with animal models to confirm that SNP variants on RIPK1 rs17548629 are associated with the progression of lung cancer." (PMID 32368189, 2020). "After adjustments for general demographic characteristics and environmental factors, under the co-dominant genetic model the risk of lung cancer in carriers with the RIPK1 rs17548629 TT genotype was 1.671-fold (95% CI 1.01 to 2.766) that of the CC genotype carriers." (PMID 32368189, 2020). "After adjustments for general demographic characteristics and stable environmental factors, under the codominant genetic model the risk of lung cancer in carriers of the RIPK1 rs17548629 TT genotype was 1.671-fold that of CC genotype carriers (95% CI 1.01 to 2.766)." (PMID 32368189, 2020). "In lung cancer research, RIPK1 has been found to display significantly elevated expression levels in both human and mouse cancer tissues, as well as in various cancer cell lines." (PMID 41334873, 2025). "Taken together, these results suggest that acetylshikonin activates the necroptosis pathway via the RIPK1/RIPK3/MLKL axis in lung cancer cells." (PMID 38126996, 2023). "For instance, RIPK1 was highly enriched in lung cancer and pancreatic ductal carcinoma and accelerated the development and metastasis of the tumor." (PMID 35719998, 2022). "On the other hand, the upregulation of RIPK3 or RIPK1 is related to the development of glioma, lung cancer, and pancreatic cancer." (PMID 34977874, 2021). "In head and neck squamous cell carcinoma, RIPK1 expression is downregulated compared to healthy tissues, whereas in lung cancer patients and mouse models of lung cancer, RIPK1 expression is markedly elevated in the tumour tissue." (PMID 34099897, 2021). "This interaction inhibits transcription of the RIPK1 gene, affects its inhibition of inflammation or induction of programmed apoptosis and necrotic apoptosis, and then leads to malignant progression of lung cancer." (PMID 32368189, 2020). "The interaction of microRNA and SNP led to insight into the regulatory role of RIPK1 in lung cancer." (PMID 32368189, 2020). "It has been demonstrated that RIPK1 was involved in SM-induced cell death in breast and lung cancer cell." (PMID 32272907, 2020). "Associations were investigated between five genetic models (co-dominant, dominant, super-dominant, recessive, and additive) of RIPK1 gene SNPs and primary lung cancers of different pathological types." (PMID 32368189, 2020). "Additionally, a recent study revealed that reduced degradation of RIPK1 mediated by the OTUD6B deubiquitinase significantly accelerated the progression of lung cancer in patients." (PMID 41334873, 2025).
lung carcinoma (continued). "Likewise, RIPK1 expression is markedly upregulated in both clinical samples of lung cancer and cigarette smoke-exposed mice lung cancer models, and thus, RIPK1 has been suggested as a tumorigenic factor." (PMID 36361505, 2022). "An initial case–control investigation was conducted of associations between SNPs in the 3′-UTR microRNA complementary region of the RIPK1 gene and lung cancer among a young and middle-aged Han Chinese population in Fujian province (adults aged younger than 60 years)." (PMID 32368189, 2020). "Because RIPK1 can affect tumorigenesis by regulating apoptosis, we speculate that the SNP of RIPK1 is likely related to lung cancer." (PMID 32368189, 2020). "Some researchers have suggested that SNPs that are potential microRNA-binding targets in the 3′ UTR of the RIPK1 gene may be involved in the occurrence and progression of lung cancer." (PMID 32368189, 2020). "Similarly, RIPK1 expression is markedly elevated in both human lung cancer samples and mouse lung tumor models, and RIPK1 has been suggested to play an oncogenic role." (PMID 31122251, 2019). "Induction of PP2A-dependent necroptosis by FTY720 was also detected in H157 (K-Ras mutant) and H827 (EGFR mutant) human lung cancer cells, in which inhibition of RIPK1 or PP2A using necrostastin or OA and knockdown of RIPK1 or PP2Ac prevented FTY720-mediated cell death compared to controls." (PMID 23180565, 2013). "Increased phosphorylation of RIPK1/RIPK3 and MLKL activity indicates that acetylshikonin promoted necroptosis in lung cancer cells." (PMID 38126996, 2023). "For instance, the sphingosine analog FTY720, also called fingolimod, induces necroptosis in human lung cancer cells by binding to inhibitor 2 of PP2A (I2PP2A/SET oncoprotein), thus activating the PP2A/RIPK1 pathway." (PMID 36482419, 2022). "Additional priming mechanisms may include the activation of receptor-interacting protein 1 (RIPK1) or the NF-κB pathway by radiation therapy, both leading to the production and secretion of IL-1β in lung cancer cell lines." (PMID 39858071, 2025). "Another novel RIPK1 inhibitor PK68 which possesses high efficacy and conserved potency among human, mouse, and rat has been reported to effectively inhibit necroptosis and suppress metastasis of both melanoma and lung carcinoma cells in mice." (PMID 36482419, 2022). "This mutation may affect transcriptional level of the RIPK1 gene via the interaction between hsa-miR-1197 and rs17548629 in the RIPK1 3′-UTR, thereby promoting the occurrence of lung cancer." (PMID 32368189, 2020). "On the other hand, it was reported that necroptosis could be mediated by MLKL but independent of RIPK1/RIPK3 signaling in transhinol A-stimulated lung cancer cells." (PMID 36030201, 2022).
myocardial infarction (19 papers, 2015 to 2025). Gross necrosis of the myocardium, as a result of interruption of the blood supply to the area, as in coronary thrombosis. "Arctiin significantly reduced myocardial I/R injury (myocardial infarction and creatine kinase release), while decreasing the levels of necroptosis-related proteins (RIPK1/p-RIPK1, RIPK3/p-RIPK3, and MLKL/p-MLKL) in the hearts of I/R-treated rats." (PMID 37504559, 2023). "FADD upregulation promoted necrosis and improved myocardial infarction by influencing the formation of RIPK1 and RIPK3 complexes." (PMID 36348274, 2022). "In myocardial infarction, ischemia-reperfusion injury, cardiac remodeling, and myocarditis, inhibiting RIPK1/3 would interrupt the transmission of inflammatory signals, thereby reducing the damage and remodeling of cardiomyocytes." (PMID 34867386, 2021). "Lastly, to examine the effect of RIPK1 inhibition in a setting of coronary plaque rupture, which is related to clinical revascularization treatment of acute myocardial infarction, post-ischemia administration of RIPK1i reduced cardiac infarct size." (PMID 34760938, 2021). "Attention has also been paid to the role of RIPK3, which lies downstream of RIPK1 in the necroptosis signaling cascade, in myocardial infarction." (PMID 33142926, 2020). "Inhibition of RIPK1 inhibited programmed necrosis after myocardial ischemia-reperfusion, reduced myocardial infarction size, reduced inflammatory response, reduced the production of ROS, and then improved the function of cardiac remodeling in the infarcted area." (PMID 36249746, 2022). "However, to our best knowledge, few studies that have focused on the mechanism of miRNAs in myocardial infarction have been reported, particularly through the pathways involving RIPK1/RIPK3." (PMID 31248365, 2019). "In addition to Ponatinib therapy, an organosulfur compound alliin alone exerted the cardioprotective effects in an in vitro and in vivo myocardial infarction model via reducing necroptosis related RIPK1, -3 and TNFR1/2 proteins expression and, escalating the autophagy machinery." (PMID 36361505, 2022). "RIPK1 and RIPK3 mRNA and phosphorylated protein levels have been found to be significantly elevated in cardiac tissue from rodents after myocardial infarction." (PMID 33142926, 2020). "Inhibiting cardiomyocyte necrosis by suppressing receptor interacting protein kinase 1/3 (RIPK1/3) RNA synthesis and protein posttranslation decreases myocardial infarct size in an ischemia/reperfusion (I/R) injury animal model." (PMID 31024249, 2019). "Moreover, suppression of lncRNA NRF could antagonize RIPK1/RIPK3-mediated necrosis in cardiomyocytes and reduce necrosis and myocardial infarction upon ischemia/reperfusion (I/R) injury in the animal model by targeting miR-873." (PMID 35091561, 2022).
Parkinson disease (18 papers, 2018 to 2025). A progressive degenerative disorder of the central nervous system characterized by loss of dopamine producing neurons in the substantia nigra and the presence of Lewy bodies in the substantia nigra and locus coeruleus. "Increased levels of RIPK1 expression and activation were demonstrated in cellular and animal models of Parkinson’s disease." (PMID 35054920, 2022). "In a Parkinson’s disease model, pharmacological inhibition of RIPK1 mitigated mitochondrial morphological alterations and dysfunction in dopaminergic neurons, indicating the beneficial impact of blocking necroptosis on Parkinson’s disease and suggesting its potential for therapeutic target." (PMID 39058145, 2024). "In addition, RIPK1 is emerging as a therapeutic target in Alzheimer’s and Parkinson’s disease, in which irregular neuronal cell death occurs." (PMID 37359541, 2023). "Furthermore, since hsa-miR-425 boosted MLKL phosphorylation by targeting RIPK1 transcripts, hsa-miR-425-5p depletion was connected to the cellular mechanism of Parkinson's disease." (PMID 35371342, 2022). "Moreover, upon inhibition of RIPK1 by Nec-1, neuronal degradation was reduced to only half compared to untreated cells in a Parkinson disease (PD) model." (PMID 31766571, 2019).
ulcerative colitis (18 papers, 2017 to 2025). An inflammatory bowel disease involving the mucosal surface of the large intestine and rectum. "An ATP competitive RIPK1 kinase inhibitor GSK2982772 is now in clinical phase II for treating ulcerative colitis, and another RIPK1 inhibitor DNL758 has been initiated for phase II study in cutaneous lupus erythematosus patients." (PMID 36358573, 2022). "Given the histological similarity between IBD (particularly ulcerative colitis) and HAEC, it is plausible that aberrant RIPK1 signaling also contributes to HAEC pathogenesis." (PMID 39489847, 2024).
hepatocellular carcinoma (17 papers, 2017 to 2025). A malignant tumor that arises from hepatocytes. "Furthermore, short-term fasting triggered hepatic inflammation in Ripk1-hepKO mice, as indicated by elevated expression of inflammatory markers and increased compensatory proliferation, potentially linked to hepatocellular carcinoma markers." (PMID 39886919, 2025). "The aberration of RIPK1 has been extensively established to be implicated in the pathogenesis of multiple categories of solid cancers by altering cell survival, such as pancreatic, colorectal, hepatocellular cancers, etc.." (PMID 37462822, 2023). "RIPK1 leads to excessive activation of Caspase-8 and promotes hepatocellular carcinoma progression." (PMID 36110223, 2022). "They found that the GG genotype of the SNP of RIPK1 rs2272990 positively correlated with tumor-node-metastasis stage and lymph node metastasis of hepatocellular carcinoma, and negatively correlated with hepatic ischemia–reperfusion injury and prognosis of liver resection." (PMID 32368189, 2020). "Luedde and colleagues demonstrated that IKKα and IKKβ regulate biliary homeostasis and promote hepatocellular carcinoma by phosphorylating receptor-interacting protein kinase 1 (RIPK1), which is involved in both apoptosis and programmed necrotic cell death (necroptosis), independent of NF-κB." (PMID 28587092, 2017). "For instance, high RIPK3 expression predicted a favorable prognosis in colorectal cancer (CRC), whereas low RIPK1 expression contributed to an unfavorable prognosis in hepatocellular carcinoma (HCC)." (PMID 35711565, 2022). "In hepatocellular carcinoma (HCC) patients, increased RIPK1, RIPK3, and phosphorylated MLKL levels were positively correlated with increases in tumor-infiltrating CD3+ and CD8+ T-lymphocytes." (PMID 38799433, 2024). "On the other hand, another study showed that combined genetic deletion of RIPK1 and TRAF2 in liver parenchymal cells contributed to the development of hepatocellular carcinoma, suggesting a suppressive role of TRAF2 in HCC tumorigenesis." (PMID 37081115, 2023). "Necroptosis related proteins RIPK1, RIPK3 and MLKL were highly expressed in hepatocellular carcinoma cells and tumor tissues with Sorafenib treatment, which means that Sorafenib activated the necroptosis pathway in vitro and in vivo." (PMID 33440739, 2021). "Mice with liver parenchymal cell (LPC)-specific NEMO deficiency (NEMOLPC-KO) spontaneously develop steatohepatitis and hepatocellular carcinoma (HCC), which is driven by RIPK1 kinase-dependent hepatocyte apoptosis." (PMID 32269263, 2020).